ODR4 (odr-4 GPCR localization factor homolog)
Description:
May play a role in the trafficking of a subset of G protein coupled receptors.
Synonyms: C1orf27; TTG1; FLJ20505; odr-4
Tractability: Antibody: UniProt predicts a signal peptide or a membrane-spanning region; the Human Protein Atlas places it where antibodies can reach. PROTAC: ubiquitination databases record sites on it; its protein half-life has been measured.
Gene: Protein-coding gene on chromosome 1 (186,375,505 to 186,421,378, forward strand). Ensembl gene ENSG00000157181.
Subcellular location: Membrane
Subcellular location (Human Protein Atlas): Nucleoplasm; Plasma membrane
Gene Ontology:
Biological process: intracellular protein localization
Cellular component: membrane
Genetic constraint (gnomAD): Loss-of-function variants: 21 observed, 22.26 expected, observed/expected ratio (o/e) 0.94, 90% interval 0.67 to 1.36. The upper end of that interval is the gene's LOEUF score, 1.36, which puts it in group 5 of 6, group 1 being the genes least tolerant of losing a copy. Missense variants: 268 observed, 279.43 expected, observed/expected ratio (o/e) 0.96, 90% interval 0.87 to 1.06. Synonymous variants: 101 observed, 94.85 expected, observed/expected ratio (o/e) 1.06, 90% interval 0.9 to 1.26.
Homologues: Orthologues: chimpanzee ODR4 (99% identical), macaque ODR4 (98% identical), rabbit ODR4 (89% identical), dog ODR4 (88% identical), pig ODR4 (88% identical), mouse Odr4 (85% identical), rat Odr4 (84% identical), guinea pig ODR4 (79% identical), tropical clawed frog odr4 (48% identical), zebrafish odr4 (44% identical).
Diseases named in the same sentence as ODR4 in open-access papers:
ODR4 is named in the same sentence as 6 diseases in open-access papers, as found by Europe PMC text mining. Sharing a sentence is not in itself a finding about the gene and the disease. The quoted sentences say what the papers report.
hepatocellular carcinoma (1 paper, 2021). A malignant tumor that arises from hepatocytes. "The frequent trend of CN-gain of TPR and ODR4 in chromosome 1q may indicate that CN-gain of TPR and ODR4 plays a role in the progression of DPHCC, while chromosome 11 has little effect on the transformation of this hepatocellular carcinoma subtype." (PMID 33854600, 2021).
lung adenocarcinoma (1 paper, 2026). A carcinoma that arises from the lung and is characterized by the presence of malignant glandular epithelial cells. "AHNAK2, CAVIN1, and ODR4 have all been linked to metastatic processes in lung adenocarcinomas or non–small cell lung cancer, pointing to a potential overlap in functionality for homing or microenvironment adaptations." (PMID 41543394, 2026).
adenocarcinoma (1 paper, 2026). A common cancer characterized by the presence of malignant glandular cells. "For instance, AHNAK2 and CAVIN1 have been linked to proliferation and migration in different cancers and AHNAK2 and ODR4 were identified as potential biomarkers for adenocarcinomas." (PMID 41543394, 2026).
tumor (1 paper, 2026). "Using a mouse model of metastatic TNBC, we identified four new CTC surface markers, AHNAK2, CAVIN1, ODR4, and TRIML2, which specifically stain tumor cells." (PMID 41543394, 2026).
ODR4 also shares sentences with these, for which no sentence is quoted: cancer (1 paper); non–small cell lung cancer (1).